SOX4 (SRY-box transcription factor 4)
Diseases named in the same sentence as SOX4 in open-access papers (continued):
Sharing a sentence is not in itself a finding about the gene and the disease.
hepatocellular carcinoma (43 papers, 2012 to 2026). A malignant tumor that arises from hepatocytes. "SOX4 expression is not only associated with biliary reprogramming and steatohepatitis but also with hepatocellular carcinoma progression." (PMID 39194690, 2024). "In hepatocellular carcinoma, it acts directly on cyclin D3, causing cell cycle arrest and regulating the expression of SOX4, thereby controlling the growth of hepatocellular carcinoma." (PMID 38002064, 2023). "In clinicopathological analysis, they also indicated that the nuclear overexpression of SOX4 was observed in tumor cells of hepatocellular carcinoma tissues, which was correlated with diminished risk of recurrence and improved overall survival time in patients." (PMID 22510499, 2012). "In particular, LINC00908 is responsible for hepatocellular carcinoma progression by increasing the stability of SOX‐4." (PMID 40344383, 2025). "To investigate the expression levels of SOX4 in hepatocellular carcinoma (HCC), we first analyzed its mRNA expression using the TCGA database and dataset GSE144269." (PMID 40399256, 2025). "Our previous study identified a molecular interaction promoting hepatocellular carcinoma (HCC) growth induced by SOX4 and Anillin." (PMID 35924788, 2022). "SOX4 is known to have oncogenic functions in several tumors, including glioblastoma and hepatocellular carcinoma." (PMID 34993348, 2022). "HOXD-AS1 prevents miR-130a-3p mediated degradation of SOX4 through competitive binding to miR-130a-3p, thereby promoting hepatocellular carcinoma transfer." (PMID 35430805, 2022). "For instance, OIP5-AS1 increases SOX4 expression to induce hepatocellular carcinoma through sponging miR-363-3p." (PMID 33628831, 2021). "In this study, we assessed the power of sex-determining region Y (SRY)-related high-mobility group (HMG)-box 4(SOX4) gene to predict the clinical course of hepatocellular carcinoma (HCC)." (PMID 33995626, 2021). "The up-regulation of SOX4 has been detected in breast cancer, pancreatic cancer, lung cancer, prostate cancer, colon cancer, meduloblastoma, ovarian cancer and hepatocellular carcinoma." (PMID 22510499, 2012). "For instance, STAT3 could specifically promote the transcription of lncRNA HOXD-AS1 and prevented the degradation of SOX4, thus promoting the metastasis of hepatocellular carcinoma (HCC)." (PMID 41208976, 2025). "Sox4, Sox9, and Sox17 may play roles in cancer progression and metastasis in hepatocellular carcinoma." (PMID 40980324, 2025). "Finally, lenvatinib treatment can increase the expression of SOX4 in hepatocellular carcinoma cells and lead to drug resistance." (PMID 37958409, 2023). "Finally, the role of SOX4 in lenvatinib resistance and proliferation in hepatocellular carcinoma were identified in vitro." (PMID 37958409, 2023). "For instance, CXCL12 is activated by SOX4 to drive the process of hepatocellular carcinoma." (PMID 35294319, 2022). "Thus, we revealed that Sox4 facilitates HBV replication in hepatoma cells." (PMID 25970172, 2015).
hepatocellular carcinoma (continued). "To investigate whether SOX4 promotes hepatocellular carcinoma (HCC) progression via ChREBP, we conducted a series of functional rescue assays." (PMID 40399256, 2025). "In esophageal squamous and hepatocellular carcinomas, SNHG17 can promote EMT by targeting miR-338-3p/SOX4 and miR-3180-3p/regulatory factor X-box 1 (RFX1) axes, respectively." (PMID 36185210, 2022). "Notably, overexpression of SOX4-mediated CXCL12 promoter in HCC cells enhanced tumor-induced angiogenesis, contributing to distant tumor metastasis and poor prognosis in hepatocellular carcinoma (HCC) patients." (PMID 35573654, 2022). "More interestingly, we reveal that the viral-activated Sox4 in turn, facilitates HBV replication by stimulating the virus protein expression and DNA replication in hepatoma cells." (PMID 25970172, 2015). "SOX4 has been found to be over-expressed in adenoid cystic carcinoma (ACC), hepatocellular carcinoma, bladder tumors, acute myeloblastic leukemia, prostate cancer, endometrial cancer and glioblastoma." (PMID 25366337, 2014). "The three types of EpCAM-positive hepatoma cells that overexpressed SOX4 showed no increase in CD90 expression." (PMID 40253402, 2025). "Furthermore HOXD-AS1 has been demonstrated to cooperate with miR-130a to regulate SOX4 and E2F8, and promote metastasis in hepatocellular carcinoma and glioma respectively." (PMID 30823895, 2019). "A number of studies have investigated SOX4 mediated transcriptional changes in the context of prostate, hepatocellular carcinoma (HCC), small cell lung cancer and adenoid cystic carcinoma, resulting in the identification of a large number of potential SOX4 targets." (PMID 23301048, 2013). "Although SOX4 is reported to function as a survival factor during the development of neuro-progenitors and SOX4 mediates prostaglandin A2-induced apoptosis in human hepatocellular carcinoma, we did not detect a significant effect on apoptosis with SOX4 depletion in pancreatic cancer cells." (PMID 23251334, 2012).
lung carcinoma (43 papers, 2007 to 2025). "Sox2, Sox3, Sox4, and Sox9 potentially contribute to tumor proliferation, invasion, and malignancy in lung cancer." (PMID 40980324, 2025). "The SOX4 gene is often amplified and overexpressed in > 20 types of malignancies, including cancers of the lung, prostate, bladder and breast." (PMID 39052126, 2024). "In another study, shRNA was used to specifically knock down SOX4 in the Xuanwei female lung cancer cell line (XWLC-05), and experiments using nude mice revealed that this led to increased apoptosis, and decreased cell proliferation and metastasis." (PMID 39052126, 2024). "SOX4 overexpression in lung cancer is related to the mechanisms of gene amplification, and the active form synergizes to promote cell growth along with the RHOA-Q63L oncogene, suggesting its importance as a lung cancer oncogene." (PMID 36661515, 2023). "A large number of studies have found that has-miR-338-3p inhibits the proliferation and invasion of lung cancer cells by targeting SOX4, IRS2 and AKT." (PMID 35992856, 2022). "lncRNA CCAT1 activated cisplatin resistance via a mechanism relating to the miR‐130a‐3p/SOX4 axis in non‐small cell lung cancer." (PMID 31984680, 2022). "SOX4 is increased in lung cancer due to genomic amplification and contributes to the transforming ability of lung cancer cells." (PMID 33824274, 2021). "In vivo experiments demonstrated that, compared with control groups with stable knockdown of CASC15, concurrent overexpression of SOX4 significantly promoted tumor growth in nude mice bearing human lung carcinoma xenografts." (PMID 33407675, 2021). "SOX4 expression is elevated in a large variety of tumor types, including leukemia, colorectal cancer, breast cancer and lung cancer, suggesting a fundamental role in the development of these malignancies." (PMID 33407675, 2021). "Based on TCGA datasets, we observed that SOX4 expression was distinctly upregulated in lung cancer specimens." (PMID 34413915, 2021). "Introduction of miR-132 significantly suppressed the migration and invasion of lung cancer cells in vitro by targeting SOX4." (PMID 31906769, 2020). "In contrast, Sox4 was described as a DNA damage sensor in lung carcinoma cells promoting cell cycle arrest and apoptosis." (PMID 23874955, 2013). "Aside from the Sox2, the expression of Sox4 was also elevated in several types of cancer, in which lung cancer had the greatest levels of Sox4 expression." (PMID 23443092, 2012). "The relationship of Sox4 to cancerogenesis of lung cancer was further attested by a polymorphic study in patients with NSCLC." (PMID 23443092, 2012). "The attractivity of SOX family members for T-cell-based immunotherapy of tumours was documented by a recent report indicating that SOX4 is overexpressed in lung carcinoma and can serve as a target structure of CTLs." (PMID 17375044, 2007). "According to the TRN of lung cancer, SOX4, FOXM1, ETV4, HOXC6, and E2F3 are the main positive regulators, whereas SOX17, KLF4, and ZBTB16 are the main negative regulators of transcription, controlling the expression of other TFs and target genes in lung cancer." (PMID 39228892, 2024). "In lung cancer, SOX4 also exhibits functional oncogenic properties." (PMID 39052126, 2024). "Therefore, SOX17 must be downregulated and SOX4 upregulated to allow for the establishment and progression of lung cancer." (PMID 36661515, 2023). "Therefore, the knockdown of SOX4 decreased miR-130a-3p-induced cisplatin resistance in cisplatin-resistant lung cancer cells by reducing ABCG2 expression." (PMID 36778005, 2023).
lung carcinoma (continued). "The KM plot analysis showed that the overregulation of three oncogenes (SOX4, BZW2, and FOXM1) as well the downregulation of four tumor suppressors (SOX17, ZBTB16, TAL1, and KLF4) is associated with worse overall survival (OS) for lung cancer patients." (PMID 36661515, 2023). "In addition, our results indicated that upregulated hsa_circ_0020714 significantly promoted SOX4 expression in mouse lung cancer LLC cell line." (PMID 35800365, 2022). "SOX4 is overregulated in all ten lung cancer datasets, suggesting that it could be a key oncogene function in lung cancer." (PMID 36101460, 2022). "In lung cancer, miR-338-3p directly binds Sox4 to silence tumor cells’ metastasis." (PMID 34718336, 2021). "In the particular case of lung cancer, SOX4 was found to be overexpressed partially due to genetic amplification of the SOX4 locus, and increased expression of SOX4 was identified as a potential biomarker for tumor malignancy and poor prognosis in patients with NSCLC." (PMID 33407675, 2021). "Moreover, global expression analysis performed in lung cancer confirmed upregulation of the SOX4 expression signature in a panel of primary lung tumors." (PMID 33407675, 2021). "Other than the Sox2 and Sox4, Sox9 and Sox18 also showed oncogenetic properties in lung cancer." (PMID 23443092, 2012). "SOX4 is widely expressed in various types of cancer including glioblastoma, medulloblastoma, melanoma, and adenoid cystic carcinoma of salivary gland, as well as colon-, prostate-, bladder- and lung cancers." (PMID 23251334, 2012). "The regulatory function of SOX4, FOXM1, and ETV4, over other key TFs and common DEGs, was highlighted in lung cancer, establishing key co-regulatory complexes in NSCLC and SCLC." (PMID 39228892, 2024). "The global transcriptomic network analysis highlighted the impact of five TFs, SOX4, TCF3, TEAD4, ETV4, and FOXM1, in gut and lung cancer." (PMID 39228892, 2024). "On the other side, exogenous expression of SOX4 significantly abrogated the CCAT1-knockdown-mediated cisplatin sensitivity and ABCG2 lower expression in cisplatin-resistant lung cancer cells." (PMID 36778005, 2023). "Among the many predicted targets, seven genes (SOX4, ZEB2, AVL9, PTPN9, RAB22A, ITGB8 and SIX1) that have been reported to play an oncogenic role in lung cancer were further analyzed." (PMID 35287543, 2022). "We also found strong correlations between mRNA and SOX4 protein expression in CPTAC datasets including breast, uterine corpus, and lung cancer from TCGA database." (PMID 34442467, 2021). "In lung cancer, SOX4 expression is probably related to the overregulation of WNT5A; then, SOX4, FOXM1, TCF3, and JUP might form a stable protein complex with other factors and co-factors for the regulation of transcriptional targets." (PMID 39228892, 2024). "XAV-939, a Tankyrase inhibitor, has been shown to promote ferroptosis in lung cancer cells by inducing the down-regulation of SLC7A11, and inhibiting the progression of lung cancer by down-regulating lncRNA MIR503HG, sponging miR-1273c and regulating SOX4 expression." (PMID 37005430, 2023). "The seven top deregulated transcription factors (SOX4, SOX17, BZW2, FOXM1, ZBTB16, TAL1, and KLF4) consistently appear to be co-expressed with other frequent DEGs and transcription factors throughout the analysis in lung cancer and PAH." (PMID 36661515, 2023). "According to the TRN analysis, SOX4 can be regulated by HOXC6, whereas DLX5 can be regulated by SOX4, FOXM1, and ETV4, and according to the co-regulatory network analysis, they both participate in the formation of TF complexes in both subtypes of lung cancer (NSCLC and SCLC)." (PMID 39228892, 2024). "No significant changes in mean values of SOX4 and AXIN2 between non-diabetic and diabetic Metformin-taking lung cancer patients were detected." (PMID 29977599, 2018).
lung carcinoma (continued). "In lung cancer, BMP5 is a common gene but it is downregulated, as are TGF-β receptors and SMADs; therefore, none of them may be involved in the regulation of SOX4 and DLX5 expression." (PMID 39228892, 2024). "However, there was a significant correlation between SOX4 and AXIN2 mRNA levels in tumor tissues in the group of non-diabetic lung cancer patients (Spearman’s rank correlation coefficient ρ = 0.47, P < 0.0001)." (PMID 29977599, 2018).
prostate carcinoma (42 papers, 2010 to 2025). A carcinoma that arises from epithelial cells of the prostate gland. "This study aimed to evaluate the expression of P4HB and SOX4 in prostatic carcinoma and investigate their possible diagnostic or prognostic roles." (PMID 39118797, 2024). "The current study revealed that P4HB and SOX4 were significantly expressed in PAC compared to NPH which suggests their oncogenic role in prostatic carcinoma and strongly indicates its diagnostic capability which was further confirmed by ROC curve analysis." (PMID 39118797, 2024). "MiRNA-129-2-3p targets and negatively regulates the expression of SOX4, an oncogene that has been associated with the progression of prostate cancer and oral lichen planus to OSCC." (PMID 34564679, 2022). "Recent studies have also reported that SOX-4 is associated with tumorigenesis and shows higher expression in human malignant tumors, such as prostate cancer, colorectal cancer, breast cancer, lung cancer, gastric cancer." (PMID 34157052, 2021). "We also identified groups that contained validated prostate cancer oncogenes with novel associations, such as SOX4, a prostate cancer transforming oncogene, and FOXA2 and GATA4, known pioneer factors (oTFCG13)." (PMID 30314329, 2018). "Oncogene SOX4 plays an essential role in prostate cancer progression, but this gene might be associated with progression of pituitary prolactinoma." (PMID 33709028, 2021). "Earlier, we demonstrated that CUL4B promotes prostate cancer progression by establishing a positive feedback loop with SOX4, amplifying its oncogenic effects." (PMID 40203790, 2025). "We evaluated malignant characteristics related to NEPC in prostate cancer cell lines with stable overexpression or knockdown of SOX4 in vitro." (PMID 39014441, 2024). "We demonstrate that SOX4 promotes NE trans-differentiation by activating the SOX4/PCK2 pathway to induce carbohydrate metabolism reprogramming in prostate cancer." (PMID 39014441, 2024). "This study aims to investigate P4HB and SOX4 expression in prostatic carcinoma, their possible roles, and clinical significance." (PMID 39118797, 2024). "And the mechanism of miRNA-214-5p inhibiting the proliferation of prostate cancer cells were analyzed by detecting the expression difference of downstream factors of SOX4 pathway." (PMID 34863188, 2021). "The overexpression of miRNA-214-5p significantly lowered the expression level of SOX4 gene in prostate cancer cells." (PMID 34863188, 2021). "At the same time, the expression of SOX4 transcription and translation in prostate cancer tissues and normal tissues were explored." (PMID 34863188, 2021). "The expression of SOX4 showed an upregulation trend in prostate cancer cell lines and patient samples, and this upregulation was related to Gleason score or tumor grade." (PMID 34863188, 2021). "Further research results showed that inhibiting the expression of SOX4 in prostate cancer cell lines can inhibit the proliferation of cancer cells." (PMID 34863188, 2021). "The low expression of miRNA-214-5p was observed in prostate cancer tissues and cells, while high expression of SOX4 was observed in prostate cancer tissues and cells." (PMID 34863188, 2021). "Overexpression of miRNA-214-5p to prostate cancer cells significantly inhibited the proliferation of cancer cells, and the expression of SOX4 was inhibited in the transfected cell line." (PMID 34863188, 2021). "The SOX4 gene has been identified as a critical component of the PTEN-PI3K-AKT pathway in prostate cancer, and RUNX2 is a type of oncogene that unusually increases in prostate cancer cells, promoting their metastatic phenotype." (PMID 34512726, 2021). "miRNA-214-5p and miRNA-214-5p inhibitor was over-expressed in DU-145 cell lines to verify the effect of miRNA-214-5p on prostate cancer cell proliferation and SOX4 gene expression." (PMID 34863188, 2021).